INS (insulin)
Diseases named in the same sentence as INS in open-access papers (continued):
Sharing a sentence is not in itself a finding about the gene and the disease.
Hyperglycemia (continued). "The transient hyperglycaemia seen following infusion-stop was most likely attributed to the suppressed endogenous insulin production, leaving the animals temporarily hypoinsulinaemic following withdrawal of exogenous insulin." (PMID 35982111, 2022). "Both type 1 and type 2 diabetes are characterized by failure of beta cells within the islets of Langerhans of the pancreas, resulting in defective insulin secretion from the beta cells that leads to clinical hyperglycemia." (PMID 36277698, 2022). "Obesity causes a continuous elevation in plasma levels of free fatty acids, which induces hyperglycemia and impairs insulin sensitivity." (PMID 37746194, 2022). "In 2011, we detected a high prevalence of hyperglycemia among hospitalized patients in our institution and a low percentage of these patients were normoglycemic or under basal insulin regimen." (PMID 35315989, 2022). "There is defect in the pancreatic β- cell function such that as pregnancy progresses, insulin resistance increases, the insulin response subsequently becomes inadequate resulting in hyperglycaemia." (PMID 36447189, 2022). "Most of the PCPs in this study (88.9%) agree that insulin therapy should be initiated depending on the degree of hyperglycemia or HbA1c levels, especially if the patient was on a maximum dose of oral antihyperglycemic medications with an HbA1c > 7%." (PMID 36554673, 2022). "Autoimmunity is noteworthy in this high-risk, vulnerable population due to the high probability of becoming insulin dependent early in the disease course and having persistent hyperglycemia after GDM." (PMID 36992779, 2022). "Another pathway is through the inhibition of DPP-IV, resulting in increased insulin secretion to reduce postprandial and fasting hyperglycemia." (PMID 36496713, 2022). "Hyperglycemia and ketonemia induced by direct impairment of ß-cell function and transdifferentiation of ß-cells showing reduced insulin secretion have been reported." (PMID 35256883, 2022). "Convincing evidence indicates that persistent hyperglycaemia develops when pancreatic beta-cells fail to secrete sufficient insulin to compensate for insulin resistance." (PMID 36138030, 2022). "Insulin-sensitive tissues like adipose tissue, skeletal muscle, and cardiac muscle are less abundant in preterm than in term neonates, thereby leading to hyperglycemia by poor uptake of glucose." (PMID 36654578, 2022). "When performing the analysis for hyperglycemia similar results were produced for both cases (0.76 ± 0.03 vs. 0.76 ± 0.03, using glucagon and insulin respectively as templates—Panel b)." (PMID 35822422, 2022). "Of note, sliding-scale insulin as the only regimen is not recommended as it is a reactive method that provides insulin only after hyperglycemia." (PMID 35246230, 2022). "Failure of insulin to uptake glucose into target tissues such as muscle, liver, and adipose due to insulin resistance will lead to hyperglycemia." (PMID 36381191, 2022). "The longer the fasting time, the lower the insulin concentrations, and this postprandial hyperglycemia induces pro-inflammatory cytokines, oxidative stress, vascular endothelial dysfunction, and proteinuria." (PMID 36060962, 2022). "Histological morphological observation revealed that insulin treatment relieves islet β cells and promotes cell recovery following hyperglycemia-induced destruction." (PMID 36615827, 2022). "The patients experienced reductions in hyperglycemia, and several of them coincidentally reduced or ceased treatments with prescription drugs or insulin." (PMID 35260150, 2022). "The result of this is the loss of the physiological communication between the cells and the alteration of the feedback mediated by insulin and glucagon, resulting in hyperglycemia that feeds and perpetuates the process." (PMID 35216512, 2022). "Reduced mortality, especially from sepsis, is observed after insulin treatment in critically ill adults and extremely preterm infants with hyperglycemia." (PMID 35989990, 2022).
Hyperglycemia (continued). "Hyperglycemia generated by food intake with a high glycemic index increases the insulin secretion of pancreatic beta cells high insulin blood concentrations decrease the hematic glucose levels." (PMID 36678524, 2022). "Owing to the limitations and off-target side effects of antidiabetic drugs, exercise-induced control of hyperglycemia and increased insulin sensitivity is a preferred line of strategy to manage “diabesity” associated complications." (PMID 36531176, 2022). "Ultra-rapid insulin formulations control postprandial hyperglycemia; however, inadequate understanding of injection site absorption mechanisms is limiting further advancement." (PMID 35671972, 2022). "β cell dysfunction results from an inability to detect elevated glucose levels to stimulate an appropriate secretion of insulin, which exacerbates hyperglycemia." (PMID 36034454, 2022). "Cross‐correlation analysis demonstrated a small in‐phase coordination between insulin and glucagon concentrations during fasting, which inverted during hyperglycemia." (PMID 35822422, 2022). "Despite increasing dose adjustments, insulin-meal matching, and compliance with insulin, she experienced episodes of unexpected hyperglycaemia and hypoglycaemia." (PMID 35350098, 2022). "The D-LED PBM group in the 4-week study also showed improved hyperglycemia and liver enzyme levels, with relatively preserved pancreatic islets and increased serum insulin and GLP-1 levels." (PMID 36359885, 2022). "Subsequently, hyperglycemia treated by insulin increases the conversion of glucose 6-phosphate to glycogen by glycogen synthase, which is itself stimulated by insulin and hyperglycemia." (PMID 35655318, 2022). "TD improved blood glucose level and insulin function in diabetic rats; accordingly, TD activates glucose metabolism and insulin synthesis preventing glucose intoxication due to hyperglycemia in TDM." (PMID 35725834, 2022). "The most recent advance in SAP is the use of a hybrid closed loop system, which can automatically make adjustments to the wearer’s basal insulin in the presence of both hypo- and hyperglycaemia." (PMID 36714590, 2022). "The Lispro insulin required to manage postoperative hyperglycemia was also less in the magnesium group (odds ratio, 0.67; 95% CI, 0.47–0.95; p = 0.024)." (PMID 35683428, 2022). "Beta-pancreatic cells shift as the disease progresses, and insulin secretion is unable to preserve glucose homeostasis, resulting in hyperglycemia." (PMID 35356248, 2022). "These cells are insulin producing, and their destruction results in sub-optimal levels of circulating endogenous insulin and elevated levels of blood glucose (hyperglycemia)." (PMID 36083870, 2022). "The mechanism of effect of this group is based on inhibition of glucagon secretion, ensuring insulin release in response to hyperglycemia, also leading to delayed gastric emptying, which provides for enhanced satiety." (PMID 35629267, 2022). "An adjustment of the glucose infusion rate in parenteral nutrition and insulin administration are effective measures for controlling hyperglycaemia in sepsis patients in our centre." (PMID 36962870, 2022). "In a glucose-induced diabetic zebrafish model, Eysenhardtia polystachya (EP)-loaded silver nanoparticles (AgNPs) were likewise reported to boost pancreatic β-cell survival and insulin secretion-enhanced hyperglycemia." (PMID 36440220, 2022). "Insulin resistance represents a decrease in insulin signaling and results in hyperglycemia and T2DM." (PMID 36290725, 2022). "When glucose levels in the blood remain high, beta cells are stimulated to secrete higher insulin levels to counteract hyperglycemia." (PMID 36532060, 2022). "In animal studies, impaired dendritic development is described in offspring born to rats with streptozotocin-induced hyperglycemia in pregnancy—possibly through abnormal insulin/insulin-like growth factor 1 (IGF1) signaling in the fetal brain." (PMID 35472047, 2022).
Hyperglycemia (continued). "To avoid hyperglycemia after glucose administration, we conducted simple arginine stimulation tests to determine the insulin secretory reserve." (PMID 35530849, 2022). "Type 2 diabetes (T2D) is primarily associated with obesity and insulin resistance, accompanied by a failure of beta cells to secrete sufficient insulin to overcome the resistance, thus leading to hyperglycemia." (PMID 35448529, 2022). "In diabetics, there is a delayed response to injury due to impaired functioning of the leukocytes and fibroblast and reduced insulin in the face of hyperglycemia." (PMID 35265364, 2022). "Several studies showed that FoA can ameliorate hyperglycemia and insulin sensitivity by altering mitochondrial dysfunction while exerting antioxidant activities." (PMID 35213966, 2022). "Various preclinical studies have demonstrated that MSC-EVs show effective roles in alleviating hyperglycemia in diabetic animal models by improving β-cell mass, promoting insulin sensitivity, and increasing glucose uptake and metabolism in peripheral tissues." (PMID 36297643, 2022). "Sustained hyperglycemia and insulin hyposensitivity lead to the dysfunction of various tissues and organs." (PMID 35355561, 2022). "Increased mTORC1 activity causes inhibition of pyruvate dehydrogenase which reduces pyruvate entry into the tricarboxylic acid cycle and partially accounts for the hyperglycaemia-induced reduction in oxidative phosphorylation and insulin secretion." (PMID 36376280, 2022). "T2DM is a chronic metabolic disorder with hyperglycaemia resulting from the disturbance of insulin action on peripheral tissues such as the liver and muscle and/or pancreatic insulin secretion." (PMID 35057577, 2022). "Despite administration of three antihypertensive drugs, the patient’s blood pressure remained above 140/90 mmHg, potassium supplementation was started due to hypokalaemia and insulin due to hyperglycaemia." (PMID 36111117, 2022). "The insulin signaling pathway is of great significance for maintaining average blood glucose levels and avoiding complications of hyperglycemia." (PMID 35701780, 2022). "A limited response of serum glucose, urea N, and TG with the addition of GAA or CGAA in stage 1 and stage 2 was consistent with the findings in mice, indicating that supplementary UGAA or CGAA affected insulin homeostasis and ameliorates hyperglycemia." (PMID 35990281, 2022). "Accordingly, successful establishment of experimental models of T1D, characterized by chronic hyperglycemia, have been predominantly accomplished by employing chemicals that destroy the activity of pancreatic β-cells, triggering impaired insulin secretion." (PMID 35899107, 2022). "Despite hyperglycaemia, fasting insulin levels were significantly lower in HFD‐fed Il1r1Hep−/– mice compared to WT littermates." (PMID 36101976, 2022). "Reduce fasting blood glucose, insulin levels, serum lipids, hyperglycemia, hyperlipidemia and oxidative stress." (PMID 35369480, 2022). "Oral hypoglycaemic drugs and insulin are used to improve glycaemic control when dietary intervention alone is insufficient to control maternal hyperglycaemia in women with GDM." (PMID 35334931, 2022). "Alloxan, a diabetogenic agent, has been shown to cause extensive selective damage to pancreatic β-cells via reactive oxygen species generation, resulting in a partial or complete defect in insulin action and hyperglycemia." (PMID 36301972, 2022). "The inhibition of DPPIV can attenuate hyperglycemia by increasing incretin availability and insulin levels." (PMID 36551281, 2022). "DM is a systemic metabolic disorder characterized by hyperglycemia, hyperlipidemia, hyperaminoacidemia, and hypoinsulinemia in which insulin action and insulin production both are reduced." (PMID 35685725, 2022). "Previous studies have shown that higher plasma glucose concentrations in calves fed HL from MR increase insulin concentrations, with the insulin response generally preventing hyperglycemia by glucose excretion." (PMID 36272981, 2022).
Hyperglycemia (continued). "Constant high glucose levels will initiate hyperinsulinemia and resistance of peripheral tissues to insulin, resulting in hyperglycemia." (PMID 36230918, 2022). "It was observed that GPD2−/− mice are resistant to hyperglycemia induced by diet, independently of the insulin secretion stimulated by glucose." (PMID 35890109, 2022). "Considering the benefit of GCs in patients with respiratory failure due to COVID-19, there is a need for specific insulin therapy to address steroid-induced hyperglycemia." (PMID 35246230, 2022). "Adaptive mechanisms to compensate and to prevent hyperglycemia include an increase in both β-cell mass and insulin secretion." (PMID 35742878, 2022). "In islets from β-cell-specific G3PP deletion mice, ATP production and insulin secretion are enhanced at high glucose levels, suggesting that the glycerol shunt plays a role in preventing insulin hypersecretion in hyperglycemia." (PMID 36139067, 2022). "Increased VEGF production in diabetic patients can be a result not only of periods of hyperglycaemia and hypoglycaemia, but also of exogenous insulin intake or genetic factors." (PMID 36349176, 2022). "Many in vivo and in vitro studies have shown that hyperglycemia, insulin treatment, and different oral antidiabetic drugs can ameliorate the lethal progression of aortic diseases." (PMID 36330007, 2022). "Among this group, hyperglycemia occurs when pancreatic β-cells, after prolonged production of large amounts of it, cannot produce enough insulin to compensate for its defect." (PMID 35742405, 2022). "The pancreas of diabetic patients can be sluggish to secrete insulin in response to a meal which consequently lead to a condition known as post-prandial hyperglycaemia (elevated blood glucose level)." (PMID 35335362, 2022). "It indicates that only women with prior GDM, characterized by hyperglycemia and impaired insulin secretion in our study, exhibited unique IL13 and RELA overexpression profiles." (PMID 36499008, 2022). "Insulin therapy is almost always concomitant with episodes of hypo and hyperglycemia even with highly controlled insulin dosages while they never happened in non-diabetics in regard to state variable feedbacks." (PMID 36535972, 2022). "Short-acting GLP-1 receptor agonists have demonstrated modest reductions of fasting blood glucose levels and substantial reductions of postprandial hyperglycemia by stimulating fasting insulin secretions and decreasing glucagon secretion." (PMID 35054924, 2022). "Administration of insulin, as well as hyperglycemia, activates p38 MAPK in vascular smooth muscle cells." (PMID 35600869, 2022). "Pancreatic infiltrated islet-autoreactive T cells destroy the β-cells, resulting in insufficient insulin secretion, that elicits hyperglycemia." (PMID 36405706, 2022). "Phosphatidylinositol-3-kinase–induced hyperglycemia tends to be temporary as it activates a feedback mechanism leading to higher circulating insulin levels, restoring glucose homeostasis." (PMID 35016012, 2022). "Blood glucose and serum insulin were monitored in the following time until the patient had sustained extreme hyperglycaemia, the sign of exhausted injected insulin." (PMID 36440205, 2022). "Informed from the results of the pilot study, the principal investigator (GRB) obtained funding to set up a birth cohort titled ‘Maternal Antecedents of Adiposity and Studying the transgenerational role of Hyperglycaemia and Insulin’ (MAASTHI)." (PMID 36130760, 2022). "We evaluated the effects of preoperative hyperglycemia on perioperative stroke in subgroups of patients stratified by age, sex, previous ischemic stroke, preoperative insulin medication, surgical category, and surgery length." (PMID 36337712, 2022). "Hyperglycemia decreases BBB permeability to insulin, resulting in lower brain insulin levels and lower insulin-promoted neural and glial cell activity." (PMID 36620773, 2022).
Hyperglycemia (continued). "Dysfunction of β cells leads to impaired or insufficient insulin secretion, which results in hyperglycemia and diabetes." (PMID 35669692, 2022). "It has been demonstrated that anthocyanin-rich bilberry extract ameliorates hyperglycemia and insulin sensitivity via the activation of AMP-activated protein kinase in diabetic mice." (PMID 36144260, 2022). "In human trials, applying 40 g of dried sea buckthorn to 200 g yogurt and 50 g glucose has been suggested to suppress peak insulin response and stabilize postprandial hyperglycemia." (PMID 35684164, 2022). "The action in the uptake of glucose in adipose tissue is the primary target site in glucose metabolism and to obtain glucose homeostasis by controlling hyperglycemia through insulin-stimulated glucose uptake." (PMID 36042748, 2022). "Within 4 weeks of diet intake, mSAD-fed mice developed hyperglycemia, glucose intolerance, and reduced insulin sensitivity relative to CON mice." (PMID 36105576, 2022). "Skeletal muscle is the primary site of dietary glucose processing; therefore, muscle sensitivity to insulin action is critical for the development of systemic IR and hyperglycemia." (PMID 35795140, 2022). "Ventricular dysfunction without coronary atherosclerosis and hypertension is driven by hyperglycemia, hyperinsulinemia and impaired insulin signaling." (PMID 35204091, 2022). "An analysis of retrospective medical records of patients with T2DM who initiated insulin due to uncontrolled hyperglycemia by oral agents was conducted from 2015–2020 in the University of Gondar Comprehensive Specialized Hospital." (PMID 35617250, 2022). "These mice exhibited hyperglycaemia and lower plasma insulin levels under a high fat diet together with decreased islet mass." (PMID 35614067, 2022). "Parenteral-nutrition (PN)-induced hyperglycemia increases morbidity and mortality and must be treated with insulin." (PMID 35631667, 2022). "Based on limited human studies and animal experiments, a diet rich in polyphenols can reduce fasting plasma glucose (FPG) levels and postprandial hyperglycemia, as well as improve acute insulin secretion and insulin sensitivity." (PMID 36386943, 2022). "GRP78 is essential for proinsulin synthesis, and up-regulation of GRP78 can increase insulin secretion in response to hyperglycemia, while down-regulation of GRP78 can decrease insulin secretion and lead to significantly low levels of insulin." (PMID 36498048, 2022). "Hyperglycemia provokes a compensatory increase in insulin production by the pancreatic β-cells and hyperinsulinemia." (PMID 35453469, 2022). "Hyperglycemia, which entails increased water consumption, weight reduction, and polyphagia due to the inefficient use of glucose in tissues due to low insulin levels, is common in T1DM." (PMID 35276790, 2022). "Metformin or glibenclamide combined with honey (four-week treatment) increased insulin secretion, decreased fructosamine levels and improved hyperglycemia, and reduced creatinine, bilirubin, triglycerides levels, and very low-density lipoprotein cholesterol." (PMID 36632095, 2022). "In sporadic cases (1.9%) insulin was administered to Group 0 patients who had hyperglycemia in the days following admission." (PMID 36038896, 2022). "T2DM is a chronic metabolic disorder characterized by a hyperglycemia status resulting primarily from the combination of progressive impairment of insulin secretion by pancreatic islet β-cells and insulin action on target tissues." (PMID 36197412, 2022). "Our data suggest that the absence of autophagy in hepatic CD11c+ cells results in increased weight gain, fasting hyperglycemia, insulin insensitivity, glucose intolerance, hepatomegaly, liver inflammation, and steatosis when compared to control mice." (PMID 35301333, 2022). "In insulin-resistant individuals, the defects in this process contribute to hyperglycemia in the postprandial state." (PMID 35651975, 2022).